MMP14 (matrix metallopeptidase 14)
Diseases named in the same sentence as MMP14 in open-access papers (continued):
Sharing a sentence is not in itself a finding about the gene and the disease.
cancer (continued). "In addition, ccRCC is the leading cause of death in von Hippel–Lindau disease patients, whose aggressiveness could be due to the increase in MMP-14 expression among other molecules involved in cancer progression." (PMID 38069210, 2023). "Likewise, a decrease in MMP-14 levels was observed in cancer samples compared to the control group." (PMID 36213817, 2022). "Genes containing AS events associated with overall survival are known components of cancer-related pathways, including regulation of transcription (E2F4, ZNF730, GPBP1, POLR2J, SP2, and CIART), cell cycle (E2F4 and GTSE1), or cell-cell adhesion (CEACAM1, MMP14, EPS8L2, AP3D1, AFDN, and PAK4)." (PMID 35044822, 2022). "Therefore, MMP14 plays an extremely important role in tumors, and strengthening the role of MMP14 across cancers is of great importance and significance for the treatment, prevention, and diagnosis of cancer." (PMID 34604053, 2021). "Exosomes were shown to induce the differentiation of cancer-associated fibroblasts (CAFs) in the collagen-rich extracellular matrix (ECM) and to secrete collagen-regulatory factors such as matrix metalloproteinase-14 (MMP-14), whereas collagen type I enhanced exosome secretion." (PMID 34202855, 2021). "However, this study did not explore the mechanism of action of MMP14 across cancers, which is a deficiency of this study." (PMID 34604053, 2021). "Moreover, in carcinoma cells, substrate stiffness has been linked to EMT, which could lead to indirect changes in MMP14 expression." (PMID 31466240, 2019). "What is more, astrocytes could increase the IL-6 secretion and stimulate the expression of membrane type-1 matrix metalloproteinase (MT1-MMP or MMP14), a proteolytic enzyme known to be involved in extracellular matrix degradation and assist cancer invasion and progression." (PMID 31435515, 2018). "Moreover, by manipulating PROX1 expression we could regulate MMP14 expression in an in vivo mouse model and change the invasive properties of cancer and blood endothelial cells in vitro." (PMID 29934628, 2018). "Additionally, the serum MMP-14 levels among controls and cancer patients may be affected by an uneven distribution and shedding of MMP-14 from healthy and malignant cell membranes." (PMID 30532247, 2018). "In addition, MMP14 also plays a key role in potentiating cancer cell migration." (PMID 26001294, 2017). "Moreover, expression of the matrix metalloproteinases coded by the MMP2, MMP9, and MMP14 genes confers these cells the ability to degrade extracellular matrix proteins, an important step in various stages of cancer progression, including angiogenesis, invasiveness, and metastasis." (PMID 26110651, 2015). "In addition, sub-cytotoxic MJ decreased the specificity protein 1 (Sp1) expression and binding on MMP-14 promoter, while restoration of Sp1 expression rescued the cancer cells from sub-cytotoxic MJ-mediated defects in MMP-14 expression, migration, invasion and angiogenesis." (PMID 23394613, 2013). "The implications of MMP-2 activation by MMP-14 and the tissue inhibitor of metalloproteinases-2 are considered alongside the effect the architecture of the matrix may have when applied to a model of cancer invasion." (PMID 23565505, 2013). "Prinomastat was tested for treating advanced cancer and oesophagus cancer due to its high affinity for MMP‐2, MMP‐3, MMP‐9, MMP‐13 and MMP‐14." (PMID 41546170, 2026). "Our findings reveal an intriguing paradox: while MMP-14 appears to maintain genome stability in ACC cells, prior studies in other cancer models demonstrate that MMP-14 promotes genomic instability." (PMID 41542511, 2026). "The MMP7-expressing cancer cells frequently co-expressed MMP1, MMP14, and several Wnt-related genes, consistent with a cancer cell type at high risk of malignancy and metastasis." (PMID 42079046, 2026). "Among the 22 investigated MMPs, seven genes (MMP2, MMP3, MMP10, MMP12, MMP14, MMP15, and MMP16) were upregulated in cancer, while MMP8 was downregulated." (PMID 41728806, 2026).
cancer (continued). "Across all six probes—targeting ACE2, CATB, METAP1/2, MMP14, plasmin, and USP15—significantly elevated protease activity was observed in cancer patients compared to healthy controls." (PMID 40890441, 2025). "MMP-14 (MT1-MMP) is a membrane-bound enzyme that activates proMMP-2 for ECM degradation at the cell surface and facilitates cancer cell invasion." (PMID 41356146, 2025). "The prognostic value of high expression levels of MMP9, MMP12, MMP14, and MMP16 in various cancers, as indicated in this study, has also been reported in prior research." (PMID 39493455, 2024). "Knockdown of TUG1 not only inhibits CRC migration and invasion through the miR-542-3p/TRIB2 axis but also, by overexpressing it, regulates the miR-26a-5p/MMP14/p38 MAPK/Hsp27 axis in vitro and in vivo to accelerate cancer invasion." (PMID 39026978, 2024). "The MMP9, MMP12, MMP14, and MMP16 genes work synergistically to regulate processes such as tissue remodeling, wound healing, and cancer invasion." (PMID 39493455, 2024). "Clinical data have already confirmed that soluble factors MMP-14 and MMP-9 play roles in the effectiveness of regorafenib in relation to cancer progression and metastasis." (PMID 39199626, 2024). "mRNA expression levels of MMP-12, MMP-13, MMP-14, and MMP-19 in the cervical tissue of patients with cancer were greater than that observed in the control (p = 0.045, p = 0.025, p = 0.003, and p = 0.025, respectively)." (PMID 39247608, 2024). "Finally, both CRP and FFV PEVs significantly upregulated gene expression of ECM components (e.g. MMP14, MMP16, collagen type V alpha 1 chain, versican) as well as the genes SERPINE1 and PMEPA1, which are associated with epithelial-to-mesenchymal transition in various cancer types." (PMID 39695652, 2024). "This synthetic reagent usually emits little fluorescence until it binds to the cancer cells through AS1411 and encounters MMP-14." (PMID 36741760, 2023). "Furthermore, MMPs, including MMP9 and MMP14, may confer resistance to various cancer therapies by altering tumor vasculature to impact drug delivery, promoting survival pathways in cancer cells, or driving the acquisition of more aggressive phenotypes through EMT." (PMID 37760801, 2023). "Numerous recent studies consistently indicate that activated fibroblasts exert control over the progression and metastasis of cancer through their active secretory protein, comprising MMP11, MMP14, and FN1." (PMID 38057779, 2023). "Recent studies indicated that Snail can mediate the upregulation of several gene expressions of MMPs in cancers such as MMP-2, MMP-9, and MMP-14, and these proteases were reported to be promoters and mediators of EMT processes in cancers." (PMID 36766694, 2023). "MT-1MMP, known as MMP-14, functions as one of the crucial drivers of cancer invasion and metastasis." (PMID 38201481, 2023). "SUMO inhibitors with SUMO-unconjugated TFAP2A reduce the cancer stem cell (CSC) population by suppressing CD44 and matrix metallopeptidase 14 (MMP14) expression to limit the stemness." (PMID 37291585, 2023). "MMP, such as MMP11 and MMP14, are involved in degrading the ECM in various cancers and therefore promote metastasis and angiogenesis." (PMID 36587397, 2023). "Several of these specialized TME microenvironments are enriched by the pan-cancer survival network, for example HIF1A signaling (p = 4.27 × 10−6; FGF2, IGF2, MMP1, MMP14, MMP3, PIK3R3, SERPINE1, TGFB1)." (PMID 35106465, 2022). "The PI3K/AKT pathway also participates in extracellular matrix remodeling and VM process through activating MMP-14 and -2, facilitating the cleavage of LAMC2, thereby promoting VM-related motility of cancer cells." (PMID 36418859, 2022). "The tested OS cell lines were characterised by a cancer-related phenotype, such as increased expression of mRNA for BMP-7, as well as MMP-7 and MMP-14." (PMID 36139691, 2022).
cancer (continued). "M1-like TAMs significantly promoted the epithelial-mesenchymal transition (EMT) process, and induced the cancer-stem like cells (CSCs) by upregulating the expression of MME and MMP14 in OSCC cells." (PMID 34991668, 2022). "Many cancer-cell invasion and migration-promoting genes such as SERPINE1, PLSCR1, ITGA2, MMP14, etc. are significantly down-regulated in the IGROV1 cells." (PMID 34949722, 2022). "Mechanically, exosome-transferred MMP14 promotes the stability of CD44, the cancer stem cell marker in the recipient cells." (PMID 35223528, 2022). "Highly invasive and aggressive cancer cells overexpress MMP-14 and -2 and LAMC2, which help to form a vascular structure lined by cancer cells." (PMID 36418859, 2022). "As MMP-14 is a membrane-type MMP, and active MMP-14 is located on the cell surface, antibody-mediated therapy can block the function of MMP-14 in cancer." (PMID 36741729, 2022). "MMP14-knockout models (RM82 (#GSE173143) and SK-N-MC (#GSE173147) share common GO terms related to the metastatic potential of cancer cells, which were mostly downregulated, as evaluated by GSEA." (PMID 35955799, 2022). "The pan-cancer survival network further enriches the inhibition of matrix metalloproteases (A2M, MMP1, MMP14, MMP3, TIMP4)." (PMID 35106465, 2022). "The positive staining of Hsp70, MMP14, MMP2, and cortactin was mostly observed in the cytoplasmic of the carcinoma cells, whereas the nucleic positive signals were detected much more in the Hif1α immunohistochemical staining." (PMID 35957827, 2022). "Investigating the role of LUM is a critical field of research in cancer molecular biology because it affects MMP regulation and has been demonstrated to inhibit MMP9 and MMP14 expression." (PMID 34310653, 2021). "Lumican (57 kDa) is able to inhibit MMP-14 activity and to protect collagen degradation contributing to attenuation of MMP-14-dependent cancer cell migration and invasion." (PMID 34638415, 2021). "When GSK3β is inhibited by AKT, free β-catenin accumulate and translocate to the nucleus, ultimately activating downstream target genes such as cyclin D1, C-Myc, CD44, FN1, C-JUN, Slug, L1CAM, and MMP14; thus contributing to tumorigenesis and EMT of cancer." (PMID 34546849, 2021). "Expression levels of MMP2 and MMP14 were similar in both tissue types; MMP3 protein expression was lower in para-cancer tissues than in HCC tissues; MMP11 protein expression was higher in HCC tissues." (PMID 34376644, 2021). "While FP shows a lower proliferation than CP, its cancer cells express high levels of two CSC markers (CD44, CD133) as well as MMP14." (PMID 33672734, 2021). "Membrane-type 1 matrix metalloproteinase (MT1-MMP, MMP-14), a membrane-anchored MMP is typically expressed by stromal cells as well as cancer epithelial cells undergoing EMT." (PMID 35004699, 2021). "Other known targets of miRNAs in cancers include MMP2, MMP9, MMP13, MMP14, and MMP16 and their substrates such as type I, II, and IV collagens." (PMID 33920915, 2021). "The majority of MMPs and TIMPs were mainly expressed in cancer cells at the invasive front (MMP-9: 97.3% of the tumors, MMP-11: 98.7%, MMP-14: 94.0%, TIMP-1: 86.7%, TIMP-2: 96.7%)." (PMID 33669393, 2021). "Of particular importance is MMP-14 (MT1-MMP), which is usually found at a low level in normal cells but can reach higher levels in cancer cells." (PMID 35008569, 2021). "Our results also showed that upon peptide treatment, three proteins reported to sustain high proliferation rates in cancer cells (TRXR1, MMP14 and GPX1) were upregulated in MDA-MB-231 cells." (PMID 33499187, 2021). "DX-2400, DX-2802 and DX-2712 are three other monoclonal antibodies directed against MMP-14, MMP-9 and MMP-12, respectively, currently evaluated in preclinical cancer models." (PMID 34298680, 2021). "MMP14 and MMP2 both degrade the extracellular matrix especially collagen IV, found in basement membranes, and indeed MMP14 and MMP2 have been shown to promote cancer invasion and metastasis." (PMID 33149188, 2020).
cancer (continued). "MMP-9, MMP-14, ADAM-12 and ADAM-17 are some of the MPs that were found to have a significant role in several types of cancer." (PMID 32466129, 2020). "Expression of genes that played a pivotal role in cancer cell migration, including VEGFA, PLAU, MMP2, MMP9, and MMP14, were reduced in dose-dependent manner of stigmasterol in both cell lines." (PMID 32481565, 2020). "The invasiveness of cancer cells is likewise regulated by the lifespan of MMP-14, which depends on the pattern of its O-glycosylation, and by the internalization of MMP-14 and the subsequent degradation or recycling to the cell surface." (PMID 33379400, 2020). "They induce the formation of CAFs in peri-tumoral stroma, favor cancer cell EMT, and improve the secretion of matrix metalloproteinase 14 (MMP-14) to digest and modify collagen network." (PMID 32899718, 2020). "It has previously been reported that MMP-2 is secreted as a zymogen (pro-MMP-2), and that membrane-bound MMP-14 (MT-1-MMP), which is mainly expressed on fibroblasts and cancer cells, activates secreted MMP-2 by cleaving its pro-domain." (PMID 31726690, 2019). "MMP14, MDM2, ERBB2, SKP2 and PTGS2, which were previously identified as OGs in human cancer, also have higher rate of amplification in mutation data." (PMID 31205821, 2019). "This process is often stimulated by tumor cell-derived proteases, such as thrombin, cathepsin B, cancer procoagulant (EC 3.4.22.26), MMP-2 and MMP-14." (PMID 30927923, 2019). "Membrane type-1 matrix metalloproteinase (MT1-MMP/MMP-14) cleaves domain III of Ln-γ2 chain, which contains a laminin-EGF-like motif and promotes malignant cancer progression via EGFR and its downstream signaling." (PMID 30626121, 2019). "Cancer-derived exosomes induce the formation of CAFs in the collagen matrix to promote EMT and increase the secretion of MMP-14 to regulate collagen." (PMID 31521169, 2019). "The lipid raft-expressed MMP14, dominated by the C-terminal processed form(s), serves as the major form that is responsible for ECM degradation in cancer cells." (PMID 31439888, 2019). "The canonical proteolytic cascade that leads to enhanced cancer cell invasion is considered to be initiated by (pro)cathepsin B, which translocates from lysosomes to plasma membranes, where it may activate uPA, which in turn activates MMP-14, followed by activation of gelatinases MMP-2 and MMP-9." (PMID 28424417, 2017). "MMP-14, also known as membrane type-1 MMP (MT1-MMP), is a membrane bound MMP overexpressed in most cancer cells which is correlated to poor patient prognosis." (PMID 27531896, 2016). "Mint3-mediated HIF-1 activation depends on an invasion-promoting membrane protease MT1-MMP/MMP14 in macrophages and cancer cells." (PMID 27883071, 2016). "In vitro study, MMP-14 is known as an important activator of pro-MMP-2 at the cell surface via the involvement of TIMP2; for this reason, the interactions among MMP-14, TIMP2 and MMP-2 are of importance in cancer cell invasion and migration." (PMID 26314845, 2015). "Seven cancer cell lines were analyzed for MMP-2 and MMP-14 expression levels by Western blotting analysis." (PMID 26314845, 2015). "Since cancer cells have been shown to migrate and to invade ECM by mechanisms that involve matrix metalloproteinases, the expression of MMP-14 in B16F1 cells was analyzed using real-time PCR and Western immunoblotting." (PMID 24098450, 2013). "Like MMP-14, MMP-15 has been most widely studied for its role in cancer progression and metastasis, primarily through its capacity to cleave and activate MMP-2." (PMID 22768148, 2012). "Several lines of evidence have indicated that MMP species such as MMP-2, MMP-7, MMP-9 and MMP-14 (MT1-MMP) have key roles in invasion and metastases of cancer cells." (PMID 22015555, 2011). "It is reported that MMP14 cleaves the LAMC2 gamma -2 chain, producing a fragment release usually increased in cancer cells." (PMID 19753302, 2009).
cancer (continued). "Constitutive expression and activity of MMPs increases the invasiveness of various types of cancer cells, and we have determined characterized the expression of MMP-2, MMP-9 and MMP-14 as well as TIMP-1 and TIMP-2 mRNA in EN-1078D cells, using RT-PCR." (PMID 17894888, 2007). "MMP-2 and MMP-14 mRNA was detected primarily in reactive stromal cells whereas TIMP-2 mRNA was expressed by both stromal and cancer cells." (PMID 16776850, 2006). "These enzymes have been implicated in key cancer-associated processes such as extracellular matrix degradation (MMP14, plasmin), tumor invasion and metastasis (CATB), immune regulation and signaling (USP15), and cancer-related proteolytic processing (ACE2, METAP1/2)." (PMID 40890441, 2025). "Given the critical roles of MMPs and TIMPs in cancer biology, we hypothesized that MMP-9, MMP-14, TIMP-1, and MMP-2 could serve as prognostic biomarkers for regorafenib efficacy in mCRC patients." (PMID 39199626, 2024). "The principal MMPs involved in cancer are MMP-2, MMP-9, and, most notably, MMP-14." (PMID 36766694, 2023). "Macrophages promote cancer invasion by secreting MMPs (MMP12, MMP8 and MMP14)." (PMID 37324952, 2023). "Thus, matrix-degrading proteases, such as MMP-2, MMP-9, MMP-14 (MT1-MMP), and MMP-16 (MT3-MMP), were reported to be required for EMT progression of different cancer types." (PMID 36766694, 2023). "Apart from degrading ECM components, MMP-14 is also responsible for the activation of pro-MMP-2, pro-MMP-9, and pro-MMP-13, of which pro-MMP-2 and pro-MMP-9 activation have been claimed as a crucial step in cancer cell invasion and metastasis." (PMID 35586209, 2022). "For cancer, identified targets include VEGFB, VEGFR2, MAP2, MMP14, HNF1A, TUSC5 and KLF12." (PMID 35356223, 2022). "MMP14 is localized in the leading edge of migrating cancer cells where it proceeds extracellular matrix (ECM) remodeling by degrading protein components of the ECM and promotes cancer cell migration, invasion and metastasis." (PMID 35223528, 2022). "Moreover, we showed that the level of the GalNAc glycotope in MMP-14, EGFR, αV-, β1- and β4 integrin in highly and poorly invasive cancer cells correlated positively with their invasive potential." (PMID 35028012, 2022). "In addition, we found that macrophage subpopulations (clusters 1, 5, 7, 8, and 9) from cancer tissues expressed a certain number of immunosuppressive genes, such as VEGFA, MMP14, MMP19, S100A2, APOE, HMOX1, SLAMF7, SIRPα, LAG3 and IL18." (PMID 36158683, 2022). "Downregulation of cancer cell-expressed MMP-14 did not affect primary growth but inhibited lung metastasis in an orthotopic mouse model of TNBC." (PMID 36741729, 2022). "Studies also indicate that MMP14 regulates cell motility, cancer stemness and other important biological processes non-proteolytically." (PMID 35223528, 2022). "In this study, we investigated the relationship between MMP14 and TMB and MSI in endemic cancer." (PMID 34604053, 2021). "SNAI1 also induces MMP-14- and MMP-15-dependent BM transmigration by cancer cells." (PMID 35008569, 2021). "Cancer can produce a wide spectrum of proteases, including MMP-1, MMP-3, MMP-7, MMP-8, and MMP-14." (PMID 34769032, 2021). "Additionally, association analysis of CMTM6 mRNA levels with Wnt target genes (TCF4, LEF1, CD-44, MMP14, ENC1, ID2, PPARA, and JAG1) from the cancer genome atlas HNSCC cohort using GEPIA showed a positive correlation (r > 0.2)." (PMID 33434185, 2021). "In addition, the expression of MMP14 is closely related to the immunoosmosis and ICI level of human pan-cancer, especially in LGG, PRAD, THCA, and other tumors." (PMID 34604053, 2021). "In 1994, MMP-14 was the first membrane-bound MMP to be described and its role on invasion and metastasis has been demonstrated in animal models Also, MMP-14 predicts prognosis in cancer in general according to a recent review." (PMID 34344453, 2021).